CD47 (CD47 molecule)
Diseases named in the same sentence as CD47 in open-access papers (continued):
Sharing a sentence is not in itself a finding about the gene and the disease.
cancer (continued). "CD47 is known to be upregulated in patients with different cancer types and is considered a poor prognostic marker." (PMID 39659795, 2024). "Cui and coworkers conjugated the anti-cancer drug paclitaxel with iRGD to generate a self-assembling peptide paclitaxel-iRGD, and next, they encapsulated CD47 antibodies to produce a hydrogel (aCD47/PF)." (PMID 39409876, 2024). "Increasing evidence suggests that SIRPα-CD47 immune checkpoint blockade enhances the efficacy of cancer immunotherapy." (PMID 39318624, 2024). "Nevertheless, CD47-SIRPα axis blockade has shown anti-cancer effects and synergy with other anti-cancer therapies." (PMID 38773064, 2024). "CD47, widely expressed on the surface of various cancer cells, interacts with the macrophage-expressed SIRPα, generating a “don’t eat me” signal." (PMID 38370407, 2024). "For example, reprogramming TAMs using a ZEB1 antagonist and blocking the CD47-SIRPα pathway are state-of-the-art “normalization cancer immunotherapy” strategies that can synergistically restore the antitumour properties of immune cells in the TME." (PMID 38183060, 2024). "CD47 plays an important role in cell functional behavior and immune homeostasis related to cancer prognosis." (PMID 38832992, 2024). "Blocking the CD47-SIRPα interaction has been shown to promote the phagocytosis of cancer cells by macrophages." (PMID 38183060, 2024). "By targeting CD47 with antibodies and other agents that block the signal, phagocytic cells are able to “eat” cancer cells." (PMID 38261139, 2024). "The previous study has used a single-chain variable fragment (ScFv) derived from a mouse CD47 antibody to generate CD47-CAR-T cells targeting different cancer cell lines." (PMID 38832992, 2024). "A novel specific anti-CD47 nanobody from an immunized alpaca was engineered, exhibiting strong potency in disrupting the CD47–SIRPα interaction, a major axis in cancer immunotherapy." (PMID 38247566, 2024). "Multiple publications have reported correlations between higher CD47 mRNA or protein expression in specific cancers and poorer survival." (PMID 39201643, 2024). "In the context of hematologic malignancies, such as leukemia and lymphoma, CD47 plays a crucial role in protecting cancer cells from being phagocytosed by macrophages." (PMID 39275127, 2024). "Of interest, a deeper understanding of the regulation of CD47 expression on cancer cells at the molecular level has recently emerged." (PMID 38183060, 2024). "The future unfolds with the promise of transformative breakthroughs in cancer therapeutics, propelled by our ongoing exploration of the intricate interplay between CD47 and SIRPα." (PMID 39040441, 2024). "Combined targeting of multiple immune checkpoints, particularly CD47/SIRPα and PD-1/PD-L1, has gained synergistic effects in cancer treatment." (PMID 38462636, 2024). "More and more research are now increasingly focusing on the potential of CD24 as a novel target in cancer treatment, spurred by the need to find more effective and safer treatment options in light of the setbacks experienced with CD47-targeted therapies." (PMID 38881902, 2024). "As a result, disrupting the CD47–SIRPα axis has emerged as a promising target in cancer immunotherapy, with extensive ongoing research." (PMID 38247566, 2024). "Recently, it was shown that CD47 expression on cancer cells inhibits cancer cell exclusion by myeloid cells and regulates the cytotoxic function of NK cells." (PMID 39160226, 2024). "Cancer cells escape the innate immune response by means of SIRPα-CD47 interaction which provides a ‘‘don’t-eat-me’’ signal to the effector immune cells like neutrophils and macrophages." (PMID 39318624, 2024). "The CD47-signal regulatory protein alpha (SIRPα) axis, discovered in the late 2000s, was the first identified checkpoint inhibiting cancer phagocytosis through innate immunity." (PMID 38971872, 2024).
cancer (continued). "DS-1103a inhibited SIRPα-CD47 interaction and enhanced antibody-dependent cellular phagocytosis of Dato-DXd and T-DXd against human cancer cells." (PMID 38843278, 2024). "One promising treatment in cancer therapy is targeting CD47, a transmembrane glycoprotein widely expressed on the surface of various cells." (PMID 38429732, 2024). "The identification of small molecules with dual-blocking effects on PD-1/PD-L1 and CD47/SIRPα interaction is crucial for cancer treatment." (PMID 38462636, 2024). "CD47 on the cancer cell membrane and its receptor signal-regulatory protein alpha on TAMs are another pair of immune checkpoints that inhibit the activation of macrophages against cancer." (PMID 38386265, 2024). "The CD47/SIRPα pathway plays a crucial role in regulating immune responses, particularly in the context of cancer immunotherapy." (PMID 39040441, 2024). "Even though a clinically effective antibody against CD47 is still missing, strong preclinical results have already shown the importance of DEMs in terms of cancer immune evasion." (PMID 39767726, 2024). "Nonetheless, these results demonstrate induction of a generally potent anti-cancer antibody response B16F10 in a CD47 KO context." (PMID 37066426, 2024). "The results showed that CD47 expression was positively correlated with infiltration of CD8 + T cell in almost all cancer types." (PMID 38720108, 2024). "Through the natural trimerization of DSP107 via the 4-1BBL trimerization domain, binding to CD47 on cancer cells disrupts the CD47-SIRPα interaction." (PMID 38720108, 2024). "MPS1 kinase inhibition (MPS1i)-induced chromosomally unstable cancer cells are maximally cleared when IgG-opsonized and depleted of the CD47 macrophage checkpoint." (PMID 38805560, 2024). "The ligand of SIRPA is CD47, which is known as a “don’t eat me” signal and is highly expressed on cancer cells compared with normal cells." (PMID 38920727, 2024). "Therapeutic antibodies and a SIRPα-Fc fusion decoy designed to block the interaction between CD47 and SIRPα have entered multiple clinical trials and provided anecdotal evidence for efficacy in some cancers." (PMID 38495618, 2024). "The anti-CD47 scFv conjugated with MNP was examined by magnetic activated cell sorting (MACS) for its activity against CD47+ on surface cancer cells." (PMID 39156005, 2024). "Through T cell co-culture experiments, it can be established that CD47 knockout cancer cells exhibit reduced T cell depletion compared to wild-type cancer cells." (PMID 38720108, 2024). "CD47 is indeed overexpressed on the surface of various cancer cells and correlates with poor prognosis for several cancer types." (PMID 39217459, 2024). "We can use this knowledge and create therapy which will block CD47 on cancer cells and by this we can reactivate proper function of macrophages and dendric cells." (PMID 38892394, 2024). "Contrary to other studies reporting that chemotherapy induces upregulation of CD47 in several cancer indications, we observed a marked decrease in CD47 expression after NACT in most OC patients." (PMID 39138571, 2024). "Cancer cells can overexpress CD47, an innate immune checkpoint that prevents phagocytosis upon interaction with signal regulatory protein alpha (SIRPα) expressed in macrophages and other myeloid cells." (PMID 38414061, 2024). "Targeting CD47 blockade can enhance macrophage-mediated phagocytosis of cancer cells, presenting a promising avenue for cancer immunotherapy." (PMID 39588148, 2024). "The feasibility of using anti-CD47 and -SIRPα blocking antibodies for the treatment of various cancers is currently being evaluated in phase I/II clinical trials." (PMID 39039207, 2024). "CD47/SIRPα plays its part not only in cancer but also is crucial for red blood cell maintenance under physiological conditions." (PMID 38892394, 2024). "Crucially, recent investigations into CD47 have encountered a substantial impasse, signifying a pivotal moment in the advancement of cancer immunotherapy." (PMID 38881902, 2024).
cancer (continued). "The co-expression heat map showed a relationship between CD47 expression in pan-cancer and T-cell exhausted genes." (PMID 38720108, 2024). "Identified as a transmembrane protein present on red blood cells (RBCs), CD47 is a 47-50 kDa membrane protein currently known to be expressed by a variety of healthy cells in addition to cancer cells." (PMID 38638433, 2024). "This interaction is hijacked by cancer cells through the upregulation of CD47 expression on their surface, which balances prophagocytic signals and enhances the ability of cancer cells to evade innate immunity." (PMID 38983860, 2024). "Targeting CD47 on cancer cells, which binds with the SIRPα myeloid inhibitory receptor expressed on myeloid cells and makes them unresponsive against cancer cells, is a novel way of rescuing phagocytic abilities of TAMs." (PMID 38703051, 2024). "The expression of CD47 on cancer cells, akin to the PD-1/PD-L1 interaction inhibiting T cell activity, can impede myeloid cell-mediated clearance." (PMID 39040441, 2024). "High levels of either CD36 or CD47 are both prognostic indicators of poor outcomes for cancer patients." (PMID 38218979, 2024). "The prevailing evidence indicates that high CD47 expression on the surface of cancer cells functions in those cancers as an immune checkpoint by engaging its inhibitory counter-receptor, signal regulatory protein-α, on innate immune cells." (PMID 39201643, 2024). "The potential of CD47 as an important checkpoint in cancer therapy stems from its critical role in balancing the inhibitory and stimulatory functions of myeloid cells." (PMID 38638433, 2024). "Targeting the CD47-SIRPα signaling system in anticancer therapy is a promising strategy for cancer treatment because this pathway regulates both the innate and the adaptive immune systems." (PMID 39795582, 2024). "Others have reported the therapeutic efficacy of CD47 blockade with anti-CD47 antibody on various cancers in preclinical models." (PMID 38920727, 2024). "Anti-CD47 antibodies have been the focus of drug development in current immunotherapy efforts, as they inhibit the CD47-SIRPα interaction and promote cancer cell destruction by macrophages." (PMID 38429732, 2024). "Disguised as autologous cells through the CD47 protein, cancer cm@NPs escape immune surveillance and prolong circulation time." (PMID 39217459, 2024). "CD47 has emerged as a key player to promote these processes across diverse cell types, including various cancer cells." (PMID 39039207, 2024). "The CD47/SIRPα axis is an innate IC that regulates phagocytosis of cancer cells by macrophages and other myeloid cells and is thus exploited by tumors to escape innate immunity." (PMID 38414061, 2024). "This CD47-SIRPα interaction, known as the “don’t eat me” signal, allows cancer cells to escape immune surveillance." (PMID 38429732, 2024). "Cancer cells exploit this balance to evade immune detection, and therapies targeting CD47 aim to shift it in favor of immune-mediated clearance." (PMID 39682299, 2024). "This signal can be therapeutically targeted by a blocking anti-CD47 antibody, which was demonstrated to be efficacious in certain types of cancer such as Non-Hodgkin lymphoma." (PMID 38992659, 2024). "The CD47-SIRP axis has proven to be a valuable immunotherapy target in cancer, and the use of anti-CD47 antibodies in various solid tumors is now being studied." (PMID 38165484, 2024). "Therapies that block the CD47/SIRPa axis stimulate macrophage engulfment and destruction of cancer cells in preclinical models and show encouraging signs of efficacy in ongoing clinical trials for solid and hematologic malignancies." (PMID 38483480, 2024). "In this situation, many bispecific antibodies have emerged; one arm blocks CD47, while the other arm binds to common cancer antibody targets." (PMID 38464520, 2024).
cancer (continued). "A robust association exists between CD47 and the exhaustion of CD8 + T cells, potentially enabling immune evasion by cancer cells and thereby contributing to adverse prognostic outcomes." (PMID 38720108, 2024). "Recently, it was reported that an anti-CD47 mAb capable of Fc-FcγR interaction between the mAb and macrophages enhances anti-cancer activity in vivo." (PMID 38474078, 2024). "The CD47/SIRPα interaction between cancer cells and macrophages serves as a crucial “don’t eat me” signal, preventing cancer cells from phagocytosis by macrophages." (PMID 39588148, 2024). "Taken together, these data indicate that IFT57 mRNA generally exhibits stronger correlations with improved or decreased cancer survival than CD47 mRNA expression." (PMID 39201643, 2024). "Ongoing clinical trials involving CD47 antibodies across various cancer types further underscore the potential of targeting this pathway for innovative immunotherapeutic strategies." (PMID 39594611, 2024). "Recent clinical trials have focused on blocking the CD47–SIRPα interaction for cancer immunotherapy." (PMID 38426113, 2024). "Examination of CD47 coexpressed genes in 29 TCGA cancer types identified IFT57 as a gene that is highly coexpressed with CD47 mRNA in carcinomas from multiple tissues." (PMID 39201643, 2024). "The present results confirm that at least two known pharmacologic regulators of CD47 mRNA expression in other cancers similarly regulate the expression of IFT57 mRNA." (PMID 39201643, 2024). "It behoves researchers to accept the ambiguity in CD47, acknowledge its pleiotropism, and tolerate the current setbacks taking them as an inflection point for finding meaningful approaches to cure cancer, autoimmune, and other inflammatory diseases." (PMID 38362603, 2024). "Cluster differentiation 47 (CD47), which was down-regulated by metformin, is a cell-surface glycoprotein, the overexpression of which in cancers is correlated with poor prognosis." (PMID 39796103, 2024). "In both heterotopic and orthotopic xenograft mouse models, CD47 downregulation significantly suppressed the proliferation and metastasis of cancer cell lines." (PMID 39594611, 2024). "CD47 is broadly overexpressed across cancer types and represents a potentially widely applicable target for therapeutic blockade in cancer patients." (PMID 38992659, 2024). "A major mechanism by which cancer cells evade the innate immune system is the expression of CD47, which is a cell surface protein that interacts with signal regulatory protein α (SIRPα) on the surface of macrophages to block phagocytosis." (PMID 38183060, 2024). "In this review, we discuss about various small molecule modulators of targets such as STING/ENPP1, TLR, NLRP3, and SIRPα-CD47 which are key players in the innate immune system working against cancer." (PMID 39318624, 2024). "It is worth mentioning that the correlation between CD8 + T cells infiltration and CD47 is the highest in these cancer types (COAD, DLBC, ESCA, HNSC-HPV-, LIHC, LUAD, LUSC, PAAD, STAD)." (PMID 38720108, 2024). "CD47 overexpression is observed in various types of cancers, and this upregulation is considered a significant mechanism for evading innate immunity surveillance." (PMID 38247566, 2024). "That means that one of the main roles of CD47 is blocking phagocytosis which can lead to cancer cells being undetected by macrophages." (PMID 38892394, 2024). "In immunotherapy, blocking the CD47/SIRPα interaction can enhance the immune system’s ability to target and eliminate cancer cells." (PMID 39040441, 2024). "CD47’s overexpression in cancer cells makes it a compelling target for neoplastic disease treatment." (PMID 39457618, 2024). "CD47/SIRPα and PD-1/PD-L1 have emerged as promising targets for cancer immunotherapy, and their combined blockade has shown superior antitumor effects in preclinical studies." (PMID 38462636, 2024).
cancer (continued). "Great progress has been made in targeting CD47 for cancer immunotherapy in solid tumors and hematological malignancies." (PMID 38832992, 2024). "Insteadof targeting CD47 expression on cancer cells, we exploited the phagocyticability of macrophages, resulting in a prominent uptake and silencingof SIRPα." (PMID 38558434, 2024). "Known as a “don't eat me” signal on cancer cells, ligation of signal regulatory protein alpha (SIRPα) on macrophages to CD47 prevents macrophage phagocytosis of cancer cells." (PMID 38646648, 2024). "CD47 binds to signal-regulating protein alpha (SIRPα) on macrophages to trigger the “don’t eat me” signal that protects cancer cells from macrophage-mediated phagocytosis." (PMID 38464520, 2024). "Adoptively transferred T cells and agents designed to block the CD47-SIRPα axis are promising cancer therapeutics that activate distinct arms of the immune system." (PMID 38750365, 2024). "Our study has unraveled a unique association between LGMN/SPP1+ TAMs and stemness-related cancer cells (cancer cell cluster C6 marked by co-expression of CD24, CD47 and ICAM1)." (PMID 38169544, 2024). "Since CD47-SIRPα axis inhibits phagocytosis and, consequently, clearance of cancer cells, effective blockade of this pathway would allow cells like macrophages or dendritic cells to regain their proper function." (PMID 38892394, 2024). "We selected the U937 and MCF7 cancer cell lines for this experiment due to their pronounced CD47 expression levels." (PMID 38247566, 2024). "Our observations suggest CD47 as a potential biomarker for cancer diagnosis, staging, and post-treatment monitoring." (PMID 38720108, 2024). "To validate predicted interactions of NRF-1 with CD47 promoter we first performed in-silico analysis of ChIP-seq datasets derived from different types of cancer." (PMID 39742254, 2024). "Lastly, We analysed the correlation of CD47 in pan-cancer with other immune checkpoints including immunoinhibitor molecule, MHCmolecule and immunostimula molecule." (PMID 38720108, 2024). "The ligand of SIRPA is CD47, known as a “don’t eat me” signal, which is highly expressed on cancer cells compared to normal cells." (PMID 38920727, 2024). "Cancer cells upregulate the expression of CD47 to evade immune surveillance and subsequent destruction." (PMID 38983860, 2024). "CD47, an essential anti-phagocytic molecule critical in carcinogenesis, is known to hinder the elimination of cancer cells by macrophages." (PMID 38892314, 2024). "Accumulating evidence indicates that in various human cancers, the CD47-SIRPα axis is required for escape from innate immune surveillance." (PMID 38183060, 2024). "Strategies have been developed to regulate TAM functions through nanoparticles, such as reshaping M2 TAMs into M1 anti-tumor macrophages and blocking the CD47-SIRPα pathway to enhance cancer immunotherapy." (PMID 39420203, 2024). "In long-term coculture assays, we found that anti-CD47 antibodies or KRASG12C inhibitors (sotorasib or adagrasib) inhibited cancer cell growth over time but generally had only moderate effects as single agents." (PMID 38483480, 2024). "CD47-blocking antibodies can interfere with the interaction of CD47 with signal regulatory protein-α (SIRPα), thereby promoting macrophages to phagocytose cancer cells." (PMID 39290697, 2024). "Phagocytosis of ‘self’ cells including cancer cells is generally inhibited by the macrophage checkpoint interaction between SIRPα on the macrophage and ubiquitously expressed CD47 on any target cell." (PMID 38805560, 2024). "Inhibition of CD47 signaling has been proved to be to induce Sirpα-dependent phagocytosis, thereby enhancing the phagocytosis activity of innate cells against cancer cells and targeting the innate immune regulatory system." (PMID 38832992, 2024). "CD47 represents a potentially effective and widely applicable target for immune checkpoint-based and cancer immunotherapy." (PMID 39795582, 2024).